COL27A1 (collagen type XXVII alpha 1 chain)
Description:
Plays a role during the calcification of cartilage and the transition of cartilage to bone.
Synonyms: KIAA1870; MGC11337; FLJ11895; STLS
Tractability: Antibody: its Gene Ontology location is reachable by antibodies, with high confidence; UniProt places it where antibodies can reach, with medium confidence; UniProt predicts a signal peptide or a membrane-spanning region. Other modalities: an approved drug acts on it.
Gene: Protein-coding gene on chromosome 9 (114,155,537 to 114,312,511, forward strand). Ensembl gene ENSG00000196739.
Subcellular location: Secreted, extracellular space, extracellular matrix
Pathways (Reactome):
Extracellular matrix organization: Assembly of collagen fibrils and other multimeric structures; Collagen biosynthesis and modifying enzymes; Collagen chain trimerization
Developmental Biology: Developmental Lineage of Pancreatic Ductal Cells
Signal Transduction: MET activates PTK2 signaling
Gene Ontology:
Molecular function: extracellular matrix structural constituent conferring tensile strength; extracellular matrix structural constituent
Biological process: extracellular matrix organization; skeletal system development
Cellular component: extracellular matrix; collagen type XXVII trimer; endoplasmic reticulum lumen; extracellular region; collagen type XVII trimer; fibrillar collagen trimer
Genetic constraint (gnomAD): Loss-of-function variants: 103 observed, 225.21 expected, observed/expected ratio (o/e) 0.46, 90% interval 0.39 to 0.54. The upper end of that interval is the gene's LOEUF score, 0.54, which puts it in group 2 of 6, group 1 being the genes least tolerant of losing a copy. Missense variants: 2,274 observed, 2,439.8 expected, observed/expected ratio (o/e) 0.93, 90% interval 0.9 to 0.96. Synonymous variants: 981 observed, 951.08 expected, observed/expected ratio (o/e) 1.03, 90% interval 0.98 to 1.09.
Homologues: Orthologues: macaque COL27A1 (97% identical), pig COL27A1 (88% identical), mouse Col27a1 (81% identical), rat Col27a1 (80% identical). Paralogues in human: COL24A1 (39% identical), COL5A1 (35% identical), COL11A1 (35% identical), COL11A2 (34% identical), COL5A3 (33% identical), COL2A1 (27% identical), COL1A1 (27% identical), COL3A1 (26% identical), COL4A5 (26% identical), COL5A2 (26% identical), COL4A2 (26% identical), COL4A1 (26% identical), and 25 more.
Diseases named in the same sentence as COL27A1 in open-access papers:
COL27A1 is named in the same sentence as 35 diseases in open-access papers, as found by Europe PMC text mining. Sharing a sentence is not in itself a finding about the gene and the disease. The quoted sentences say what the papers report.
Steel syndrome (13 papers, 2017 to 2026). A rare genetic bone disease characterized by short stature, bilateral congenital hip dislocation, radial head dislocation, carpal coalition, scoliosis, pes cavus, and atlantoaxial subluxation. "Of these, the origin of the COL27A1 Steel syndrome variant on chromosome 9 has also previously been characterized as Native American ancestry." (PMID 40554605, 2025). ",34, 35, 36 Likewise, COL27A1 is established in cartilage regulation and formation, and mutations are associated with osteochondrodysplasias in humans such as Steel syndrome which feature early hip dislocations and OA." (PMID 37619450, 2023). "A mutation in COL27A1 is identified as the cause of Steel syndrome which observed symptoms consistent with systemic bone disease." (PMID 36430375, 2022). "Mutations in COL27A1 are associated with human orthopedic disease, Steel syndrome, which includes bilateral congenital HD." (PMID 36531249, 2022). "We previously reported the association of a rare COL27A1 missense variant, c.2089G>C (p.Gly697Arg), causing Steel syndrome when in homozygosis in three members of a single family; female/male sibs and a female cousin." (PMID 32376988, 2020). "We modeled the orthologous variant in murine Col27a1 and found it recapitulates some of the major Steel syndrome associated skeletal features including reduced body length, scoliosis, and a more rounded skull shape." (PMID 32376988, 2020). "More recently, mutations in the COL27A1 gene have been associated with Steel syndrome, a genetic disorder leading to bone malformation." (PMID 32878206, 2020). "Whole genome sequencing revealed that a mutation (Gly697Arg) in the COL27A1 gene had been previously implicated as the genetic variant underlying Steel syndrome." (PMID 28895531, 2017). "To understand the biological mechanism underlying Steel syndrome, we investigated the functional role of the COL27A1 gene." (PMID 28895531, 2017). "Mutations in the COL27A1 gene have been reported to be associated with the Steel syndrome." (PMID 31482140, 2019). "Steel syndrome (STLS, OMIM# 615155) is a rare skeletal dysplasia associated with biallelic pathogenic variants in COL27A1 gene." (PMID 41788698, 2026). "This gene encodes collagen type XXVII alpha 1 chain, and mutations in COL27A1 have been associated with Steel syndrome, knee osteoarthritis and Achilles tendinopathy." (PMID 37099271, 2023). "We paid special attention to COL27A1 because the proband phenotype was compatible with Steel syndrome." (PMID 33963180, 2021). "To test for clinical features of Steel syndrome in COL27A1.pG697R carriers, we performed two analyses using EHR data." (PMID 28895531, 2017). "Individuals with Steel syndrome who are not Puerto Rican descendants have either compound heterozygous mutations or homozygous mutations of COL27A1 that are different from the Puerto Rican founder mutation." (PMID 33963180, 2021). "To evaluate the preliminary evidence from the PheWAS analysis, we performed a second analysis of EHR data that focused on a comprehensive manual chart review to examine for evidence of Steel syndrome characteristics in the COL27A1.pG697R carriers in the same manner as performed for homozygotes." (PMID 28895531, 2017).
scoliosis (3 papers, 2020 to 2024). A congenital or acquired spinal deformity characterized by lateral curvature of the spine. "Interestingly, initial findings from a Chinese cohort of subjects with scoliosis have identified enrichment for heterozygous deleterious rare variants in COL27A1 (unpublished data)." (PMID 32376988, 2020).
adenoid cystic carcinoma (2 papers, 2022 to 2023). A malignant tumor arising from the epithelial cells. "Collagen type XXVII alpha 1 chain (COL27A1) having significant changes among its expressed splice variants in BCNHL is interesting since it was recently reported as being overexpressed in adenoid cystic carcinoma." (PMID 36873459, 2022). "FABP7, as well as COL27A1, has been seen to be upregulated in head and neck adenoid cystic carcinoma." (PMID 37370820, 2023).
Hepatic fibrosis (2 papers, 2024 to 2025). The presence of excessive fibrous connective tissue in the liver. "Furthermore, the protein–protein interaction (PPI) network analysis based on the STRING database and GOIs provided insights into the functional relationships among key proteins in liver fibrosis, such as Col1a2, Col5a2, MMP9, Col4aa, Col27a1, and Col5a3." (PMID 38874114, 2024).
osteochondrodysplasia (2 papers, 2020 to 2023). A term referring to disorders characterized by abnormalities in the development of bones and cartilage. "These experiments led us to conclude that Col27a1 mutant chondrocytes are able to differentiate and secrete collagen into the extracellular matrix (ECM) and that the mechanism of disease in STLS and related osteochondrodysplasias is likely not cell-autonomous." (PMID 32376988, 2020).
pulmonary fibrosis (2 papers, 2025). Chronic progressive interstitial lung disorder characterized by the replacement of the lung tissue by connective tissue, leading to progressive dyspnea, respiratory failure, or right heart failure. "By applying the loss-of-function experiment, the COL20A1, COL27A1, and WNT11 were confirmed as key profibrotic regulators of EMT and development of pulmonary fibrosis." (PMID 40034336, 2025). "As the Collagen-I plays a crucial role in fibrogenesis and the pulmonary fibrosis is characterized by its accumulation, the reduction in Collagen-I deposition caused by knocking out the COL20A1, COL27A1, and WNT11 may indicate a potential direction for pulmonary fibrosis treatment." (PMID 40034336, 2025). "Our results demonstrate that the COL20A1, COL27A1, and WNT11 are key profibrotic regulators of IPF, and the knockout of these genes attenuated the TGF-β1-induced EMT and pulmonary fibrosis in vitro." (PMID 40034336, 2025). "To further consolidate the findings of our study, we analyzed the expression levels of COL20A1, COL27A1, and WNT11 in patients with pulmonary fibrosis." (PMID 40034336, 2025). "Importantly, significantly higher expression of COL27A1 and WNT11 was found in patients with pulmonary fibrosis." (PMID 40034336, 2025). "Additionally, in line with our findings, a strong upregulation of COL27A1 was also found in IPF lungs, indicating its potential role in mediating the onset and progression of pulmonary fibrosis." (PMID 40034336, 2025). "Altogether, all of our findings demonstrate that the COL20A1, COL27A1, and WNT11 serve as key profibrotic regulators and may play a crucial role in regulating the TGF-β1-induced EMT and the pathogenesis of pulmonary fibrosis." (PMID 40034336, 2025).
Tourette syndrome (2 papers, 2015 to 2024). A neurologic disorder caused by defective metabolism of the neurotransmitters in the brain. "Recently, a genome-wide association study has indicated associations between single nucleotide polymorphisms in the Collagen Type XXVII Alpha 1 gene (COL27A1) and Tourette syndrome in several ethnic populations." (PMID 26235311, 2015). "PCR-directed sequencing was used to evaluate the genetic contributions of three SNPs in COL27A1(rs4979356, rs4979357 and rs7868992) using haplotype relative risk (HRR) and transmission disequilibrium tests (TDT) with a total of 260 Tourette syndrome trios." (PMID 26235311, 2015).
autosomal recessive polycystic kidney disease (1 paper, 2022). An inherited disorder characterized by the development of cysts affecting the collecting ducts. "The COL27A1 variant is suggested to be responsible for the skeletal phenotypic features, whereas the homozygous variant in PKD1 is considered to be a hypomorphic dominant allele causing features of autosomal recessive polycystic kidney disease." (PMID 34974531, 2022).
cervical dysplasia (1 paper, 2017). "Finally, two other ICD9 codes were significantly associated with the COL27A1.pG697R variant; 622.10 (pGLM < 1 × 10−4; OR = 5.4; CI = 2.3–12.6), which encodes for cervical dysplasia, and 789.1 (pGLM < 2.1 × 10−4; OR = 11.6; CI = 3.2–42.2), which encodes for hepatomegaly." (PMID 28895531, 2017).
chondrodysplasia (1 paper, 2009). "We previously sequenced COL27A1 in patients with various chondrodysplasias, since mRNA and protein for type XXVII collagen were identified in cartilage." (PMID 20041163, 2009).
Cirrhosis (1 paper, 2015). A chronic disorder of the liver in which liver tissue becomes scarred and is partially replaced by regenerative nodules and fibrotic tissue resulting in loss of liver function. "Patients with cirrhosis showed increased expression in blood of eight genes coding for collagen synthesis COL4A6, COL5A1, COL11A2, COL12A1, COL27A1, COL28A1, COL23A1, COL14A1." (PMID 26317806, 2015).
cleft palate (1 paper, 2025). Cleft palate is a fissure type embryopathy that affects the soft and hard palate to varying degrees. "Consistently, the COL27A1 gene is associated with bone malformations, including hip dislocations, cleft palate, scoliosis, and craniofacial differences." (PMID 39825393, 2025).
glioblastoma (1 paper, 2017). The most malignant astrocytic tumor (WHO grade IV). "miR-455, which locates at the protein-coding gene Col27a1, has been reported to be involved in early chondrogenic differentiation regulation, down-regulation of MMP-9 during exercise, hypoxia signaling and acquired temozolomide resistance in glioblastoma cells." (PMID 28538837, 2017).
osteoarthritis (1 paper, 2019). A noninflammatory degenerative joint disease occurring chiefly in older persons, characterized by degeneration of the articular cartilage, hypertrophy of bone at the margins and changes in the synovial membrane. "We identified two loci that reached genome-wide significance in the UK Biobank: rs143384, located in GDF5 (P = 1.32 × 10−12), a gene previously implicated in osteoarthritis; and rs2808772, located near COL27A1 (P = 1.49 × 10−8)." (PMID 31482140, 2019). "In the first reported GWAS of knee pain using the UK Biobank resource, we identified variants in or near GDF5 and COL27A1, which were subsequently supported in osteoarthritis cohorts from the 23andMe, OAI and JoCo cohorts." (PMID 31482140, 2019).
preeclampsia (1 paper, 2023). Preeclampsia is a hypertensive disorder of pregnancy that is characterized by new-onset hypertension with proteinuria presenting after 20 weeks of gestation, and depending on mild or severe forms may initially present with severe headache, visual disturbances, and hyperreflexia. "Further, the meta-analysis lead variant of the COL27A1 locus is near miR-455, which has roles in cartilage development, adipogenesis, and preeclampsia, and may protect endometrial cells against oxidative stress." (PMID 37871108, 2023).
salivary gland carcinoma (1 paper, 2020). A carcinoma that arises from the major or minor salivary glands. "The gene expression pattern which was shared by SaDu and MuEp was expressed to a much lesser extent in AdCy, and collagen 27A1 (COL27A1) was upregulated in AdCy, with significantly lower expression levels in the other salivary gland carcinomas." (PMID 32878206, 2020).
tendinopathies (1 paper, 2025). "On the other hand, the GG genotype of COL27A1 rs946053 suggested the protection of tendinopathies as well as the G-A-C haplotype constructed from COL5A1 rs12722, COL27A1 rs946053 and TNC rs2104772 T>A." (PMID 40869983, 2025). "The main purpose of this study was to investigate how the functional polymorphisms within the COL5A1, COL27A1 and TNC genes impact the risk of developing tendinopathies in high-level Croatian athletes." (PMID 40869983, 2025). "The aim of this study was to investigate a possible association between the COL5A1 rs12722, COL27A1 rs946053 and TNC rs2104772 polymorphisms and tendinopathies in Croatian athletes." (PMID 40869983, 2025). "Considering previous studies conducted on other populations, this study investigated further variations within COL5A1, COL27A1 and TNC genes and related risks of developing tendinopathies." (PMID 40869983, 2025).
cancer (7 papers, 2017 to 2024). A tumor composed of atypical neoplastic, often pleomorphic cells that invade other tissues. "Further investigations will determine the precise role of this gene in PCa progression and evaluate the prognostic significance of COL27A1 in this cancer." (PMID 34828332, 2021). "We detected a significantly higher expression of COL27A1 in AdCy than in the other carcinoma entities (p-value < 0.001)." (PMID 32878206, 2020). "While COL27A1, COL1A2, and COL5A3 are encoded ECM components, experiments have found that the upregulation of COL1A2 in cancer can serve as a molecular basis for metastasis development." (PMID 31660262, 2019). "To our knowledge, we describe for the first time an upregulation of COL27A1 in a human cancer." (PMID 32878206, 2020). "COL27A1, PRUNE2, MAEA, TBC1D3, GADD45B, ANXA8 and TSPY1 have been confirmed to play a pro‐resistant role in various cancers, which reflects the reliability of the hGeCKO library screening to some extent." (PMID 39550701, 2024).
tumour (4 papers, 2019 to 2024). "Our data shows that the bone stroma induce changes in AM-1 cells in some of the matrix remodelling genes such as COL27A1, a gene that is overexpressed by tumour cells and induces ECM production." (PMID 38226014, 2024). "Of note, an overexpression of COL27A1, as in AdCy, has not been linked to any other neoplasm so far." (PMID 32878206, 2020). "Most interactions were detected between fibroblasts, tumour cells and endothelial cells, and, in particular, the CAF FB_COL27A1, FB_SERPINE1 and FB_COMP were involved in most interactions." (PMID 34238352, 2021). "As ECM production by tumour cells has also been reported, we used RNA in situ hybridisation (RNA-ISH) for COL11A1 and COL27A1." (PMID 32878206, 2020). "Conversely, RNA expression of the two exemplary collagens (COl27A1 and COL11A1) was nearly restricted to tumour cells in AdCy." (PMID 32878206, 2020).
genetic disease (2 papers, 2017 to 2020). "We link the gene, COL27A1, with a little-known genetic disease, previously thought to be rare and recessive." (PMID 28895531, 2017).
skeletal dysplasia (2 papers, 2020 to 2026). Any Mendelian diseases that affects growth and development of the skeleton. "Of note, the variants identified in COL27A1 in these three Turkish individuals with skeletal dysplasia have not been observed in any publicly available variant databases nor in ~1100 exomes from Turkish individuals sequenced as part of the BHCMG initiative." (PMID 32376988, 2020).
infection (1 paper, 2020). The state of being infected such as from the introduction of a foreign agent such as serum, vaccine, antigenic substance or organism. "We used alcian blue staining to visualize proteoglycan accumulation at different multiplicity of infection (MOIs) (10, 20, 50, and 100) for the three constructs; however, we did not observe any major or significant differences between the mutations and WT COL27A1 overexpressing cells." (PMID 32376988, 2020).
COL27A1 also shares sentences with these, for which no sentence is quoted: breast carcinoma (2 papers); musculoskeletal disease (2); Alström’s syndrome (1); ameloblastoma (1); Arthritis (1); developmental delay (1); fibrosis (1); hearing loss (1); Hepatomegaly (1); ischemic stroke (1); knee osteoarthritis (1); lung carcinoma (1); pancreatic ductal adenocarcinoma (1).